RAD52 (RAD52 DNA repair protein)
Description:
Involved in double-stranded break repair. Plays a central role in genetic recombination and DNA repair by promoting the annealing of complementary single-stranded DNA and by stimulation of the RAD51 recombinase.
Tractability: Small molecule: a high-quality ligand is known. Antibody: the Human Protein Atlas places it where antibodies can reach. PROTAC: ubiquitination databases record sites on it; a small molecule that binds it is known.
Target class: Other nuclear protein
Safety:
Unwanted effects reported when the protein is acted on. In parentheses: how it was acted on, where the effect was seen, and who reports it.
grade 3-4 neutropenia (source: ClinPGx)
Gene: Protein-coding gene on chromosome 12 (910,870 to 990,053, reverse strand). Ensembl gene ENSG00000002016.
Subcellular location: Nucleus
Subcellular location (Human Protein Atlas): Nuclear speckles; Plasma membrane
Pathways (Reactome):
DNA Repair: HDR through MMEJ (alt-NHEJ); HDR through Single Strand Annealing (SSA)
Metabolism of proteins: SUMOylation of DNA damage response and repair proteins
Gene Ontology:
Molecular function: DNA binding; identical protein binding; protein binding; single-stranded DNA binding; protein-macromolecule adaptor activity
Biological process: cellular response to oxidative stress; DNA double-strand break processing involved in repair via single-strand annealing; DNA recombination; regulation of nucleotide-excision repair; double-strand break repair; double-strand break repair via homologous recombination; double-strand break repair via single-strand annealing; mitotic recombination; telomere maintenance; DNA recombinase assembly; DNA repair
Cellular component: nucleus; protein-containing complex; protein-DNA complex; nucleoplasm; site of double-strand break
Genetic constraint (gnomAD): Loss-of-function variants: 49 observed, 52.45 expected, observed/expected ratio (o/e) 0.93, 90% interval 0.74 to 1.18. The upper end of that interval is the gene's LOEUF score, 1.18, which puts it in group 5 of 6, group 1 being the genes least tolerant of losing a copy. Missense variants: 464 observed, 531.66 expected, observed/expected ratio (o/e) 0.87, 90% interval 0.81 to 0.94. Synonymous variants: 183 observed, 204.08 expected, observed/expected ratio (o/e) 0.9, 90% interval 0.79 to 1.01.
Homologues: Orthologues: chimpanzee RAD52 (96% identical), macaque RAD52 (92% identical), pig RAD52 (72% identical), rabbit RAD52 (72% identical), dog RAD52 (71% identical), mouse Rad52 (70% identical), rat Rad52 (68% identical), guinea pig RAD52 (53% identical), tropical clawed frog rad52 (53% identical), zebrafish rad52 (49% identical).
Diseases named in the same sentence as RAD52 in open-access papers:
RAD52 is named in the same sentence as 65 diseases in open-access papers, as found by Europe PMC text mining. Sharing a sentence is not in itself a finding about the gene and the disease. The quoted sentences say what the papers report.
breast carcinoma (34 papers, 1999 to 2024). "In pathogenic BRCA2 and to lesser extent BRCA1 germline mutation carriers, the presence of RAD52 p.Ser346Ter was associated with reduced risk of breast cancer." (PMID 37578974, 2023). "We sought to identify immune cell types that significantly (two-sample t-tests; p < 0.05) differed in activity across breast cancer patient groups with high and low expression of RAD52 and PBX2 linked to their survival outcomes." (PMID 37445737, 2023). "RAD52 serves as a potential target for the treatment of BRAC-deficient breast cancer, as RAD52 loss is tolerated much better by healthy human cells than BRAC-deficient cells." (PMID 37893069, 2023). "The putative association of RAD52 delins with breast cancer susceptibility was investigated using geographically matched case-control cohorts." (PMID 37578974, 2023). "Synthetic lethality accompanied by decrease in RAD51 foci was also observed in cells depleted of RAD52 and the other breast cancer susceptibility gene, BRCA1." (PMID 36107942, 2022). "A RAD52 S346X truncation variant with reduced SSA activity decreases the risk of developing breast cancer in women with BRCA2 germline mutations." (PMID 36107942, 2022). "Some RAD52 mutations that affect the SSA function or decrease RAD52 association with DNA can suppress certain BRCA2 associated phenotypes in breast cancers." (PMID 36107942, 2022). "RAD52 S346X was highly significantly associated with reduced risk of breast cancer for BRCA2 carriers; each copy of the minor allele was estimated to confer a per‐allele HR of 0.69 (95% CI, 0.56 to 0.86, P = 0.0008)." (PMID 32175645, 2020). "There also was evidence of association of RAD52 S346X with reduced breast cancer risk for BRCA1 carriers." (PMID 32175645, 2020). "RAD52: The C allele of SNP rs7963551, positioned in the 3′UTR let-7 binding site of RAD52, reduces risk of breast cancer (OR = 0.84; CI: 0.75–0.95)." (PMID 30897768, 2019). "Our data confirm that synthetic lethality can be induced in BRCA1-deficient breast cancer cells through depletion of RAD52, possibly through the accumulation of a toxic fork repair intermediate." (PMID 29145865, 2017). "Previous studies found that RAD52 depletion in BRCA2-defective breast cancer cells is associated with spontaneous and radiation-induced chromosomal aberrations." (PMID 29145865, 2017). "These include Rad52, the human Rad51 paralogs Rad51B, Rad51C, Rad51D, Xrcc2, and Xrcc3, and breast cancer susceptibility gene Brca2." (PMID 21129202, 2010). "Moreover, cyclin E1 amplification is associated with increased RAD52 expression in breast cancers, suggesting that Rad52 mediates RST." (PMID 39456601, 2024). "Our investigation revealed deletion alleles in HSD17B14 and RAD52 that showed significant enrichment in the hereditary cohort and could therefore represent novel moderate-risk alleles for breast cancer." (PMID 37578974, 2023). "As the two of the identified RAD52 delins carriers were compound heterozygotes for p.Ser346Ter, and one for p.Tyr415Ter (altogether 3/27, 11%), this suggests potential additive effects for the observed RAD52 alterations in breast cancer predisposition." (PMID 37578974, 2023). "The observation that Rad52 S346X decreases the risk of cancer in BRCA mutants suggests that Rad52 inhibitors may also be a tool for the reduction of breast cancer risk in this subset of patients." (PMID 36010882, 2022). "RAD52 is shown to be associated with breast cancer susceptibility genes BRCA1 and BRCA2." (PMID 34484285, 2021). "In these carriers, the presence of RAD52 S346X allele was significantly associated with reduced risk of breast cancer: 159 RAD52 S346X heterozygotes did not have breast cancer compared to 118 RAD52 S346X heterozygotes who had breast cancer." (PMID 32255263, 2020). "Combined loss of BRCA2‐mediated DNA repair by homologous recombination and RAD52‐mediated single‐strand annealing may result in cell death and reduce breast cancer risk." (PMID 32255263, 2020).
breast carcinoma (continued). "The RAD52 S346X allele was associated with a reduced risk of developing breast cancer in BRCA2 carriers [per‐allele hazard ratio (HR) = 0.69, 95% confidence interval (CI) 0.56–0.86; P = 0.0008] and to a lesser extent in BRCA1 carriers (per‐allele HR = 0.78, 95% CI 0.64–0.97, P = 0.02)." (PMID 32175645, 2020). "The present finding that RAD52 S346X reduces cancer risk in BRCA mutation carriers suggests that RAD52 inhibitors may also be used to reduce breast cancer risk in BRCA1/2 mutation carrier." (PMID 32255263, 2020). "Thus, the cell death seen in BRCA1-deficient breast cancer cells with RAD52 depletion requires the HR endonuclease EEPD1." (PMID 29145865, 2017). "However, when EEPD1 is also depleted in the RAD52-depleted BRCA1-deficient breast cancer cells, the synthetic lethality is completely abolished." (PMID 29145865, 2017). "Loss of heterozygosity of RAD52 is related to breast cancer." (PMID 25004928, 2014). "The combined prevalence for the RAD52 and HSD17B14 alleles in the hereditary breast cancer cohort was as high as 5%." (PMID 37578974, 2023). "The RAD52 p.Ser346Ter/delins compound heterozygotes (Her7 and Uns1) were diagnosed with breast cancer at the age of 47 and 50 years, respectively." (PMID 37578974, 2023). "The protein expression of PBX2 and RAD52 assessed with immunohistochemistry were prognostic of breast cancer survival outcomes." (PMID 37445737, 2023). "RAD52 delins carriers from the hereditary cohort were diagnosed with breast cancer at the age of 26, 28, 34, 36, 47, 54 and 78, respectively (mean 43 years), the mean for this cohort otherwise being 45 years (range 26–89 years)." (PMID 37578974, 2023). "Genome-wide investigation of rare coding region CNVs in 98 high-risk Northern Finnish breast cancer cases revealed recurrent alterations in RAD51C, RAD52 and HSD17B14 genes." (PMID 37578974, 2023). "We demonstrate that ComBiNE is efficacious in a BRCA‐mutant breast cancer model, by editing the RAD52 gene and inhibiting PARP, leading to substantial anti‐tumor effects in vivo." (PMID 37485817, 2023). "Of these, RAD51C duplication has previously been described, whereas the RAD52 delins and HSD17B14 deletion CNVs were characterized and investigated here for the first time for their association with breast cancer susceptibility." (PMID 37578974, 2023). "Here, we performed whole-exome sequencing based analysis of rare CNVs in 98 hereditary breast cancer cases and identified recurrent alterations in RAD52, RAD51C and HSD17B14 genes." (PMID 37578974, 2023). "Extending these findings to a human system, the survival of Polθ- and BRCA1-co-depleted CAL51 human basal breast cancer epithelial cells was improved by low-concentration RAD52 inhibitor or treatment with a low concentration of RAD52 siRNA." (PMID 38030626, 2023). "Her7 had five other breast cancer cases in the family, of which two were confirmed as RAD52 delins carriers along with one male pancreatic cancer case, but no additional compound heterozygotes were identified." (PMID 37578974, 2023). "Key to this process is the breast cancer susceptibility genes BRCA1 and BRCA2 as well as the accessory RAD52 gene." (PMID 36530474, 2022).
breast carcinoma (continued). "In a recent study, a truncating variant of RAD52 has been found to significantly reduce the breast cancer risk in BRCA2 mutation carriers, which supports a role for RAD52 as a genetic modifier of cancer predisposition associated with BRCA2 loss." (PMID 32255263, 2020). "A mechanistic study by Crosby and coworkers found that the forced expression of miR-373 induces a reduction in NER proteins, RAD23B and RAD52, in the breast cancer cell line MCF-7." (PMID 31191653, 2019). "RAD52 function in mammalian cells first emerged with the discovery of its important backup role to BRCA (breast cancer genes) in HR." (PMID 31569559, 2019). "To further test these data, we independently performed RAD52-SIRF in MDA-MB-231 breast cancer cells and in MCF10A, which are spontaneously immortalized normal mammary epithelial cells." (PMID 29475976, 2018). "This study demonstrates that the synthetic lethality seen when RAD52 is depleted in BRCA1 mutant breast cancer cells depends on the HR endonuclease EEPD1." (PMID 29145865, 2017). "When EEPD1 was co-depleted with RAD52 in BRCA1-/- breast cancer cells, levels of micronuclei and nuclear bridges were reduced to levels comparable to those seen in control cells." (PMID 29145865, 2017). "We depleted RAD52 in MDA-MB-436 BRCA1-/- breast cancer cells, stained nuclei with DAPI and measured nuclear abnormalities." (PMID 29145865, 2017). "In this study we show that EEPD1 is required for death of BRCA1 mutant breast cancer cells that have been depleted of RAD52." (PMID 29145865, 2017). "When we measured HU-stressed replication fork degradation in BRCA1 mutant breast cancer cells we found that depleting RAD52 or EEPD1 led to less stressed replication fork degradation, but co-depletion of both restored degradation to control levels." (PMID 29145865, 2017). "As expected, BRCA1-/- breast cancer cells were sensitive to HU (control siRNA), and this was exacerbated by RAD52 depletion." (PMID 29145865, 2017). "In BRCA2-deficient cells, including certain types of breast cancer, RAD52 substitutes for the missing BRCA2 by recruiting RAD51 to the site of DNA breaks, suggesting that BRCA2 and RAD52 play very similar roles in the HDR pathway." (PMID 25809609, 2015). "The RAD52 protein was overexpressed in breast cancer cells (MCF7, AU565, BT474, and MDA453) compared with the immortalized breast cells (MCF10A), and its mRNA expression was not significantly different in breast cancer tumors compared with normal breast tissues." (PMID 37445737, 2023). "This suggests a role for RAD52 and HSD17B14 in hereditary breast cancer susceptibility." (PMID 37578974, 2023). "In the unselected breast cancer cohort (patients unselected for the family history and age at disease onset), additional twenty RAD52 delins carriers were identified (20/1983, 1.0%, P = 0.85, OR = 1.13, 95% CI = 0.54–2.36), but this frequency remained similar to that in controls (0.9%)." (PMID 37578974, 2023). "The CNVs that disrupted RAD52 and HSD17B14 genes showed enrichment among cases with a family history of the disease and/or early disease onset, suggesting a role for these alterations in breast cancer susceptibility." (PMID 37578974, 2023). "Cytoplasmic retention renders this RAD52 variant nonfunctional leading apparently to attrition of BRCA2-deficient breast cancer cells." (PMID 34887904, 2021). "In simple terms, hazard ratio represents the ratio of the incidence of breast cancer in carriers of RAD52 S346X minor allele and those without the minor allele." (PMID 32255263, 2020). "One BRCA2 mutation carrier who was homozygous for the minor RAD52 allele had breast cancer, and three homozygotes did not have breast cancer." (PMID 32255263, 2020).
breast carcinoma (continued). "In addition, breast cancer samples with low RAD52 expression had more insertions/deletions and fusions, supporting the ability of RAD52 to suppress a-NHEJ pathway." (PMID 31799622, 2020). "When XRCC4 or LIG4 were depleted in the EEPD1/RAD52 co-depleted BRCA1-deficient breast cancer cells, no significant reduction in cell survival was observed." (PMID 29145865, 2017). "In addition, an increase of ~ 30% in clonal cell survival was observed in the EEPD1/RAD52/XRCC4 triple-depleted breast cancer cells compared to the EEPD1/RAD52 co-depletion cells respectively." (PMID 29145865, 2017). "Interestingly, the impact of the RAD52 S346X allele on ovarian cancer was similar to that observed for breast cancer, but the hazard ratios were not significant because of the smaller sample size." (PMID 32255263, 2020). "To test this hypothesis, we applied cell survival assays, immunofluorescence staining, DNA fiber and western blot analyses to look at the correlation between cell survival and genome integrity in control, EEPD1, RAD52 and EEPD1/RAD52 co-depletion BRCA1-deficient breast cancer cells." (PMID 29145865, 2017). "One of these compounds, adenosine 5’-monophosphate (A5MP), selectively inhibited the growth of BRCA1-deficient HCC1937 breast carcinoma cells (adenosine was added to the cells and phosphorylated intracellular), even though that RAD52 does not have a nucleotide binding site." (PMID 27649245, 2016). "The protein expression of RAD50, RAD52, and PBX2 was confirmed in breast cancer cell lines MCF7, AU565, BT474, and MDA453 and immortalized breast epithelial cell line MCF10A." (PMID 37445737, 2023). "The protein expression of FGF-2, RAD52, RAD50, PBX2, MAP2K2 (MEK2), and S100P was also validated with immunohistochemistry in invasive breast cancer tumor tissues." (PMID 37445737, 2023). "Frequency of RAD52, HSD17B14 and RAD51C CNV carriers in the studied breast cancer cases and controls." (PMID 37578974, 2023). "Both RAD50 and RAD52 are functionally involved in DNA repair, and their protein expression was largely correlated with the focal adhesion protein NEDD9 in breast cancer cells." (PMID 37445737, 2023). "The protein expression of RAD52, RAD50, PBX2, MAP2K2 (MEK2), and S100P was also validated with immunohistochemistry in invasive breast cancer tumor tissues." (PMID 37445737, 2023). "New findings that RAD52 is essential for cell viability in BRCA1-, PALB2-, BRCA2- and RAD51 paralog-deficient cells but not in normal cells have suggested that RAD52 may represent an attractive therapeutic target for killing breast cancer and ovarian cancer cells." (PMID 33922657, 2021). "Our data show that depletion of EEPD1 suppresses synthetic lethality, genome instability, mitotic catastrophe, and hypersensitivity to stress of replication of RAD52-depleted, BRCA1 mutant breast cancer cells." (PMID 29145865, 2017). "Specifically we show that depletion of EEPD1 rescues the synthetic lethality of RAD52-depleted, BRCA1 mutant breast cancer cells." (PMID 29145865, 2017). "We investigate allelic losses in microsatellites of the RAD51, RAD52, RAD54, BRCA1 and BRCA2 regions, and their correlations with nine pathologic parameters in 127 breast carcinomas." (PMID 10507777, 1999). "RAD52 and PBX2 had differential protein expression among breast cancer stages." (PMID 37445737, 2023). "EEPD1was thought to be responsible for mitotic catastrophe in breast cancer cells (BRCA1 mutant) in the absence of RAD52, suggesting its critical role in cancer cell survival." (PMID 37818043, 2023). "MDA-MB-436 BRCA1-/- breast cancer cells were depleted of EEPD1 and/or RAD52 using siRNA." (PMID 29145865, 2017).
breast carcinoma (continued). "The formulation, termed combinatorial and bioorthogonal nano‐editing complex (ComBiNE), was applied as a therapeutic by incorporation of the drug olaparib and targeting the RAD52 gene, and could substantially suppress tumor growth in vivo in a BRCA‐mutant breast cancer model." (PMID 37485817, 2023). "Although testing of the family members did not provide strong support for the segregation of RAD52 delins with breast cancer, there appeared to be several cases with blood cancers (leukemia, lymphoma or myeloma, 5/27, 18.5%) among the first- or second-degree relatives of the index." (PMID 37578974, 2023).